CD4 (CD4 molecule)
Diseases named in the same sentence as CD4 in open-access papers (continued):
Sharing a sentence is not in itself a finding about the gene and the disease.
type 1 diabetes (continued). "We performed single cell RNA sequencing analysis of 73 longitudinal CD4+ T cell samples collected at an early age of 3–24 months from children who subsequently developed type 1 diabetes (N = 11) and their matched controls (N = 11)." (PMID 41462339, 2025). "To investigate early gene expression changes in CD4+ T cells during development of type 1 diabetes, we performed scRNA-seq of 73 longitudinal samples of CD4+ T cells isolated from PBMCs of 11 pairs of case and control children." (PMID 41462339, 2025). "Our data demonstrate that the crosstalk with CD4+/CD25− T cells during the initial phases of type 1 diabetes triggers changes in the tRF beta cell landscape that contributes to the demise of the insulin-secreting cells." (PMID 38967669, 2024). "Type 1 diabetes-associated variants of the human UBASH3A gene caused higher levels of gene expression and decreased NF-κB signaling and IL2 expression in CD4+ T cells." (PMID 38398001, 2024). "We compared CD4+ T-cell responses to a type 1 diabetes autoantigen (proinsulin C-peptide) and to a vaccine antigen (tetanus toxoid)." (PMID 39530093, 2024). "Type 1 diabetes (T1D) is an autoimmune condition that results in the destruction of insulin producing beta cells in the pancreas by CD4+ and CD8+ T cells and macrophages infiltrating the islets of Langerhans." (PMID 39568817, 2024). "These HIPs are all recognized by TCRs derived from CD4+ T cells isolated from the pancreatic islets of individuals who had type 1 diabetes." (PMID 39554513, 2024). "Administration of Insulin-MHC-Fc to type 1 diabetes patients is expected to coat insulin-reactive CD4+ T cells via T cell receptor-MHC interaction." (PMID 38097717, 2024). "In type 1 diabetes, it is well known that autoantigen presentation to CD4(+) T cells via MHC class II molecules plays a key role in the disease process." (PMID 38539228, 2024). "CNR1 expression was upregulated in circulating CD4+ T cells from individuals at type 1 diabetes onset (6.9-fold higher vs healthy individuals) and in sorted islet beta cells from donors with type 1 diabetes (3.6-fold higher vs healthy counterparts)." (PMID 38864887, 2024). "(2022) looked at the division plane orientation in CD4+ T cells in the Type 1 diabetes (T1D) context." (PMID 38495874, 2024). "A key CD4+ T cell epitope identified in type 1 diabetes is insulin B chain amino acids 9–23 (InsB9–23)." (PMID 38097717, 2024). "We found, for the first time, that individuals at the onset of type 1 diabetes display increased CB1R expression in circulating CD4+ T cells." (PMID 38864887, 2024). "While CD4 Tregs and B cells are believed to be involved in the pathological process of type 1 diabetes, their role in T2D is still under investigation." (PMID 37305035, 2023). "CD4+ response to oxPTM-INSP-6 was also commoner in type 1 diabetes than in control participants (66.7% vs 27.3%; p=0.039)." (PMID 36207582, 2023). "Deamidated peptides are instead the targets of CD4+ T cells in type 1 diabetes (T1D) and coeliac disease." (PMID 37463891, 2023). "Nt-INSP-4 induced the strongest T cell stimulation in type 1 diabetes compared with control participants for both CD4+ (p<0.001) and CD8+ (p=0.049)." (PMID 36207582, 2023). "The analysis of the results showed that the percentage of CD3+CD4+ T cells with intracellular expression of IL-4 was significantly lower in the patients with type 1 diabetes compared to the percentage of these cells in the control group (p = 0.004)." (PMID 36768715, 2023). "When comparing response to oxPTM-INSPs and Nt-INSPs among type 1 diabetes patients, we found that CD4+ response to oxPTM-INSP-6 was more frequent compared with Nt-INSP-6 (66.7% vs 27.8%; p=0.045)." (PMID 36207582, 2023). "An additional 18 fresh blood samples from participants with recently diagnosed type 1 diabetes, five with established disease, and from 11 control participants were used to evaluate, in parallel, CD4+ and CD8+ T cell activation by oxPTM-INSPs." (PMID 36207582, 2023).
type 1 diabetes (continued). "Among individuals with type 1 diabetes, the CD4+ response to oxPTM-INSP-6 was more frequent than to Nt-INSP-6 (66.7% vs 27.8%; p=0.045)." (PMID 36207582, 2023). "To address this, we measured polyclonal CD4+ T-cell responses in PBMC from people with recent onset type 1 diabetes." (PMID 36619657, 2023). "A statistically relevant higher percentage of CD4+ T lymphocytes expressing the CD69 marker was found in the group of patients with type 1 diabetes than in the control group (p = 0.029)." (PMID 36768715, 2023). "We found that Nt-INSP-4 (LVEALYLVCGERGFFYTPKT) induced the strongest stimulation in type 1 diabetes compared with control samples for both CD4+ (mean SI: 119.8±51.69 vs 6.89±3.4, p<0.001) and CD8+ T cells (mean SI: 405.8±325.5 vs 5.948±3.125, p=0.049)." (PMID 36207582, 2023). "The percentage of CD4+ T lymphocytes expressing the CD25 antigen in the patients with type 1 diabetes was statistically significantly higher than in the control group (p = 0.044)." (PMID 36768715, 2023). "Astilbin decreased TNF-α and IFN-γ production and increased CCR9 expression of CD4+ T cells, and played a protective role in the onset of type 1 diabetes." (PMID 35652039, 2022). "We also found that N CD4 T cells show the ability, albeit mild, to predict partial remission (AUC 0.68), indicating a potential biological relevance in symptomatic pediatric type 1 diabetes." (PMID 36389771, 2022). "We identify autoantibodies and autoreactive CD4+ T cells to glucokinase epitopes in the circulation of Type 1 diabetes patients and NOD mice." (PMID 35388005, 2022). "Three immune cell subsets, i.e. N CD4 T cells, pDCs and CD56bright NK cells, were found differentially represented between new-onset type 1 diabetes and all other groups in both the analysis." (PMID 36389771, 2022). "Various reports described the secretion of miR-142 in exosomes isolated from serum of transplant patients, human T-lymphocytes of type I diabetes patients or Sjögren’s syndrome, macrophages, or CD4+T-cells that activate heart myofibroblasts." (PMID 36291816, 2022). "Type 1 diabetes (T1D) is characterized by an autoimmune destruction of insulin-producing beta-cells within the pancreas by CD4+ and CD8+ T cells and by islet-infiltrating macrophages." (PMID 36142188, 2022). "Collectively, these data imply that HPSE-1 derived from at least three different cell types is required for maximum induction of Type I diabetes by a CD4+ T cell response." (PMID 35563015, 2022). "In the context of peripheral tolerance, CD4+ T cell help is usually an instigator of autoreactive CD8+ T cell effector function in several autoimmune conditions such as in type 1 diabetes and is undesirable in transplant tolerance." (PMID 34630389, 2021). "Quantification of CD4 + memory T cells can be used as an immunomarker for the diagnosis of type 1 diabetes." (PMID 34122109, 2021). "The three HIPs used here were selected based on two previous studies which described IFN-γ producing CD4 T cell clones specific for these HIPS isolated from islets of type 1 diabetes patients." (PMID 34262563, 2021). "There was a statistically significantly higher percentage (p = 0.038) and a higher number (p = 0.028) of CD3+ CD4+ T cells in the group with type 1 diabetes than in the control group." (PMID 34830017, 2021). "Reports analysing Tregs concluded that, while the frequency of circulating forkhead box P3 (FOXP3)+CD4+ Tregs is unaltered in type 1 diabetes, their regulatory activity is diminished." (PMID 33084970, 2021). "In Type 1 diabetes (T1D), CD4 T cell Th1 cytokine responses and CD8 cytotoxic T cell responses contribute to inflammation and destruction of insulin-producing β-cells." (PMID 34276700, 2021). "Autoreactive T cells, including CD8+ cytotoxic T lymphocytes (CD8+CTLs) and CD4+ helper T lymphocytes (CD4+Th), are directly responsible for autoimmune destruction of β cells in type 1 diabetes." (PMID 33690220, 2021).
type 1 diabetes (continued). "To fill those knowledge gaps, we generated BDC2.5+ NOD mice with Il-10 deficiency (BDC2.5+Il-10-/- NOD mice) and investigated the action of IL-10 in modulating diabetogenic CD4+ T cells, neutrophils and the gut microbiota in type 1 diabetes development." (PMID 34394099, 2021). "In Type 1 diabetes a baseline defect in the CD4 + T cells, including the poorly potent Tregs is too many immature CD45RA cells." (PMID 34294806, 2021). "Remarkably these neoepitopes, called hybrid insulin peptides, or HIPs, are recognized by pathogenic CD4+ T cells in the NOD mouse and human pancreatic islet-infiltrating T cells in people with type 1 diabetes." (PMID 33995402, 2021). "The pathogenesis of type 1 diabetes includes the abnormal activation of many cells: B cells, macrophages, dendritic cells, CD4+ T cells, and CD8+ T cells." (PMID 34830017, 2021). "The notion that T cell insulitis increases as type 1 diabetes (T1D) develops is unsurprising, however, the quantitative analysis of CD4+ and CD8+ T cells within the islet mass is complex and limited with standard approaches." (PMID 34433860, 2021). "Hybrid Insulin Peptides (HIPs), which consist of insulin fragments fused to other peptides from β-cell secretory granule proteins, are CD4 T cell autoantigens in type 1 diabetes (T1D)." (PMID 34113344, 2021). "D-mannose promoted the expansion of Treg cells from naive CD4+ T cells in spontaneous type 1 diabetes as well as in a TCR transgenic model of induced airway inflammation." (PMID 33402096, 2021). "In this study, we found CD4+ T‐cell proliferative responses to proinsulin‐containing autoantigens are common before and immediately after diagnosis of type 1 diabetes but decline thereafter." (PMID 34336205, 2021). "Although type 1 diabetes (T1D) has been classically described as a CD4+ T cell-mediated disease, yet B cells also play an essential role in the autoimmune destruction of pancreatic β cells." (PMID 32775471, 2020). "We replicated the initial experiment using the same pre-sorting strategy to isolate the three assessed CD4+ T cell subsets from an individual with type 1 diabetes and one healthy donor." (PMID 32580776, 2020). "A study conducted by Li and colleagues showed that the genomic DNA methylation in CD4+ T cells from the latent autoimmune diabetes in adults (LADA) with a subgroup of type 1 diabetes, was significantly increased compared to the controls." (PMID 33072796, 2020). "CD4+ T cells are one of the key immune cells contributing to the immunopathogenesis of type 1 diabetes (T1D)." (PMID 32878069, 2020). "One recent study, however, has highlighted regions of proinsulin C-peptide as generating HLA-DQ2-restricted CD4+ T cell responses in individuals with type 1 diabetes." (PMID 31612266, 2019). "We previously reported the characterisation of islet-infiltrating CD4+ T cells from a deceased organ donor who had type 1 diabetes." (PMID 31511930, 2019). "Therapy of type 1 diabetes with CD4(+) CD25 (high) CD127-regulatory T cells prolonged survival of pancreatic islets." (PMID 31889967, 2019). "Several miRNAs in natural regulatory CD4+ FOXP3+ T cells (nTreg) have been found as markers of disease risk and T cell dysfunction in high-risk type 1 diabetes individuals." (PMID 31708933, 2019). "Type 1 diabetes (T1D) results from a breakdown in immune regulation that leads to expansion of autoreactive B cells as well as CD4+ and CD8+ T cells targeting the insulin-producing beta cells of the islets of Langerhans." (PMID 31501992, 2019). "We generated a novel HLA-transgenic mouse model that expresses high-risk genes for type 1 diabetes (DRB1*03:01-DQA1*05:01-DQB1*02:01) as well as human CD80 under the rat insulin promoter and human CD4, on a C57BL/6 background." (PMID 31612266, 2019).
type 1 diabetes (continued). "Previous studies have predominantly identified GAD65 and IA-2 to be the target islet antigens recognised by CD4+ T cells or T cell clones from individuals with type 1 diabetes using the HLA-DR3 and -DQ2 restriction elements." (PMID 31612266, 2019). "NF-κB was highly activated in an accelerated model of type 1 diabetes that requires CD4+ T cells and inflammatory macrophages." (PMID 29523846, 2018). "Most remarkably, we identify a common missense variant in IL27, associated with type 1 diabetes that results in decreased functional activity of the protein and reduced expression levels of downstream IRF1 and STAT1 in CD4+ T cells only." (PMID 28248954, 2017). "CD45 was chosen as a marker for immune cells because the insulitic infiltrates in type 1 diabetes include T cells (predominantly CD8+ but also CD4+ cells), B cells, macrophages and granulocytes." (PMID 27796420, 2017). "Autoreactive CD8+ and CD4+ T cells have been assigned independent key roles in the destruction of insulin-producing beta cells resulting in type 1 diabetes." (PMID 29403481, 2017). "Loss of PD-1, but not PD-L1, was further confirmed to be responsible for the proliferation and infiltration of reactive CD4+ T cells during type 1 diabetes in an adoptive T cell transfer model." (PMID 29255458, 2017). "In a non‐infectious context, a mouse model of type I diabetes, targeting of a pancreatic cell antigen to cDC2 favors tolerogenic properties by autoreactive CD4 T cells as compared to cDC1 targeting." (PMID 28935714, 2017). "Administration of autologous, expanded CD4+CD25highCD127low Tregs to children within 2 months of type 1 diabetes diagnosis significantly increased pTreg frequency, coinciding with a decrease in dependency on exogenous insulin." (PMID 28770318, 2017). "Our previous studies showed that increased expression of the co-inhibitory receptor PD-1 in CD4+ TE/M cells from anti-IL-7Rα-treated NOD mice contributed to protection from type 1 diabetes." (PMID 28356069, 2017). "In contrast, in nonobese diabetic (NOD) mouse models, loss of PD-1, but not PD-L1, on antigen-specific CD4+ T cells resulted in increased proliferation of CD4+ T cells and infiltration of the pancreas during type 1 diabetes." (PMID 29255458, 2017). "In a group of patients with type 1 diabetes in vitro IL-33 treatment induced regulatory CD4+CD25highFOXP3+ cells." (PMID 27761063, 2016). "Taking into account these facts, the aim of the current study was to analyze the in vitro effect of IL-33 on the quantitative properties of regulatory CD4+CD25highFOXP3+ T cell population in patients with type 1 diabetes." (PMID 27761063, 2016). "In a group of patients with type 1 diabetes in vitro IL-33 treatment induced regulatory CD4+CD25highFOXP3+ cell frequencies as well as upregulating the surface expression of ST2 molecule." (PMID 27761063, 2016). "DNA vaccination is a promising strategy to induce effector T cells but also regulatory Foxp3+ CD25+ CD4+ Treg cells and inhibit autoimmune disorders such as type 1 diabetes." (PMID 27406624, 2016). "In our previous study, we found that CD4+CD25+High and CD4+ CD25+High FOXP3+ were significantly decreased in total lymphocytes and in CD4+ cells in the recently diagnosed diabetes type I pediatric patients." (PMID 27887663, 2016). "Autoreactive CD4+ T cells recognizing islet-derived antigens play a primary role in type 1 diabetes." (PMID 26973647, 2016). "This study’s aim was to investigate the effect of Aire-overexpressing DCs (Aire cells) on the functions of CD4+ T cells and the treatment of type 1 diabetes (T1D)." (PMID 26729097, 2015). "In the present study, following in vitro stimulation, we detected an increased proportion of IL-21-producing cells within the memory CD4+ Teff population in type 1 diabetes patients." (PMID 25652388, 2015).
type 1 diabetes (continued). "In contrast to IL-21, there was no convincing support for a differential frequency of IFN-γ-producing cells within the CD45RA− CD4+ T cell subset (p = 0.07) in type 1 diabetes patients as compared with controls." (PMID 25652388, 2015). "We found a 21.9% (95% CI 5.8, 40.2; p = 3.9 × 10−3) higher frequency of IL-21+ CD45RA− memory CD4+ Teffs in patients with type 1 diabetes (geometric mean 5.92% [95% CI 5.44, 6.44]) compared with healthy donors (geometric mean 4.88% [95% CI 4.33, 5.50])." (PMID 25652388, 2015). "Type 1 diabetes (T1D) results from the progressive destruction of insulin-producing pancreatic β-cells by CD4+ and CD8+ T cells." (PMID 26555789, 2015). "To extend our research in this area, we looked at the potential relationship between the concentration of analyzed cytokines, the level of serum 17β-estradiol, and the frequency of CD4+IL17A+ Th17 cells in girls with type 1 diabetes." (PMID 24523574, 2014). "For example, MDSC from tumor-bearing mice have been shown to prevent the onset of type 1 diabetes when co-transferred with diabetogenic CD4+ T cells." (PMID 24927018, 2014). "Strikingly we showed a similar upward trend in the frequency of OX-40-expressing 1,25(OH)2D3- or TX527-treated CD4+ T cells from patients with type 1 diabetes even after additional stimulation with such a robust cytokine cocktail." (PMID 25279717, 2014). "As it was mentioned, our previous studies showed the association between the −397T>C polymorphism of the estrogen receptor α gene and the quantitative characteristics of regulatory CD4+Foxp3+ T cells in girls with type 1 diabetes." (PMID 24523574, 2014). "Patients with type 1 diabetes had a decreased percentage of circulating CD4+CD25highFOXP3+ Tregs in comparison to their healthy counterparts." (PMID 24677179, 2014). "We found increased frequencies of OX-40-expressing CD4+ T cells after exposure of T cells from patients with type 1 diabetes to 1,25(OH)2D3 or TX527, suggesting increased presence of Tregs." (PMID 25279717, 2014). "Frequencies of CD4+Foxp3+ TH17 cells were also enhanced in TT bearing girls with type 1 diabetes and correlated with the level of analyzed cytokines." (PMID 24523574, 2014). "Taken together, these observations led to the conclusion that in vitro, VDR agonists can promote expansion of CD4+CD25highCD127low Tregs in control subjects and patients with type 1 diabetes." (PMID 25279717, 2014). "Type 1 diabetes (T1D) is characterized by the autoimmune destruction of the pancreatic β cells, primarily by CD4+ and CD8+ T lymphocytes, resulting in dependency upon exogenous insulin 1,2." (PMID 24773525, 2014). "We found a similar CD4-to-CD8 ratio and a similar frequency of CD4+CD25highCD127low T cells in PBMCs freshly isolated from control subjects or from patients with type 1 diabetes." (PMID 25279717, 2014). "Type 1 diabetes (T1D) is a chronic autoimmune disease resulting from a T cell-dependent (both CD4+ and CD8+) destruction of the insulin-producing β-islets of Langerhans in the pancreas, leading to insulin deficiency and persistent hyperglycemia." (PMID 23805128, 2013). "This strategy allowed production of genetically pure DM-deficient NOD mice that are defective in class II peptide acquisition and CD4+ T cell maturation and completely protected against type I diabetes." (PMID 23418596, 2013). "Type 1 diabetes (T1D) is a disease resulting from the specific destruction of beta cells within pancreatic islets by autoreactive CD4+ and CD8+ T cells." (PMID 24278195, 2013). "Our results are consistent with a reported requirement for CD4+ T cells in the NOD autoimmune prostatitis model as well as a well-studied requirement for CD4+ T cells in the pathogenesis of type-1 diabetes in the NOD genetic background." (PMID 23577183, 2013). "NOD mice and patients with type 1 diabetes have deficiencies in at least two T-cell populations with regulatory properties: NKT and CD4+CD25+." (PMID 21584225, 2011).